CHI3L1 (chitinase 3 like 1)
Diseases named in the same sentence as CHI3L1 in open-access papers (continued):
Sharing a sentence is not in itself a finding about the gene and the disease.
hypersensitivity pneumonitis (4 papers, 2018 to 2024). Hypersensitivity pneumonitis (HP) is a pulmonary disease with symptoms of dyspnea and cough resulting from the inhalation of an antigen to which the subject has been previously sensitized. "Hypersensitivity pneumonitis (HP) patients, exposed repeatedly to organic particles, present relatively high levels of Chi3l1 in their serum." (PMID 39769202, 2024).
lung adenocarcinoma (4 papers, 2015 to 2023). A carcinoma that arises from the lung and is characterized by the presence of malignant glandular epithelial cells. "H&E staining analyses of lung tumors showed that vehicle‐injected mice presented well‐differentiated lung adenocarcinomas, but less lung metastasis was showed in anti‐Chi3L1 antibody‐treated mice." (PMID 34861103, 2022).
malignant glioma (4 papers, 2016 to 2024). A grade III or grade IV glioma arising from the central nervous system. "We found CHI3L1 significantly down-regulated in the malignant glioma subclusters 1 and 3, which were identified as the preliminary states of malignant cell differentiation." (PMID 39033204, 2024). "High-grade glioma (HGG) can also be divided into three subtypes: proneural (PN), mesenchymal (MES) and proliferative (Prolif) because of their different molecular characteristics, including CHI3L1 / YKL40, SERPINE1 and PDPN." (PMID 33875619, 2021). "Analysis of the GSE7696 data revealed that PPIC, EMP3 and CHI3L1 have greater than two-fold up-regulation at the transcription level and were drastically increased in malignant gliomas when compared to non-tumor brain tissue." (PMID 27801851, 2016).
mastitis (4 papers, 2017 to 2024). Inflammation of breast tissue during lactation or postpartum due to an obstructed duct or infection. "Nevertheless, CHI3L1 has been only scarcely reported in some proteomic studies on bovine mastitis samples obtained from either natural or experimentally coliform-infected cows." (PMID 29892291, 2018). "For this purpose, the levels of the CHI3L1 protein were assessed in whey from healthy and naturally mastitis-affected cows by Western blot as well as mRNA expression in udder tissue of cows experimentally infected with Escherichia coli." (PMID 29892291, 2018). "Whey obtained from milk samples of dairy cows diagnosed with coliform mastitis (n = 7) were analyzed for the presence of CHI3L1." (PMID 29892291, 2018). "Complementing the local cytokine profiles, we at first evaluated LCN2 and CHI3L1 as potential in vivo and in vitro innate immunity modulators in the context of mastitis." (PMID 28791009, 2017). "CHI3L1 has been shown to contribute to the facilitation of bacterial invasion into the intestinal mucosa as well as to the development of acute colitis with E. coli strains distinct from mastitis strains." (PMID 29892291, 2018). "Moreover, during S. aureus-induced mastitis, a salient finding was that neutrophil recruitment only caused a limited induction of local CHI3L1 and even no increase in mammary LCN2 compared to sham inoculation." (PMID 28791009, 2017). "Moreover, our data indicated that neutrophils can be ruled out as the (only) source of LCN2 and CHI3L1, as a strong increase of both innate immune signals was absent in experimental S. aureus murine mastitis." (PMID 28791009, 2017).
Myocardial fibrosis (4 papers, 2022 to 2025). "In a multicenter cohort study, it was observed that CHI3L1/YKL-40 was significantly elevated in the serum of patients with DCM, and its levels correlated with markers of myocardial fibrosis (e.g., PIIINP) and myocardial scar area as detected via Cardiac Magnetic Resonance Imaging (CMR)." (PMID 40873950, 2025).
osteoporosis (4 papers, 2023 to 2025). A condition of reduced bone mass, with decreased cortical thickness and a decrease in the number and size of the trabeculae of cancellous bone (but normal chemical composition), resulting in increased fracture incidence. "Chi3l1 levels are increased in osteoporosis, which is regulated by enhancing METTL3-mediated m6A methylation of Chi3l1." (PMID 39769202, 2024). "Furthermore, early growth response 1 (EGR1), a transcription factor of METTL3, can promote osteoclast differentiation and osteoporosis development by regulating the METTL3/m6A/Chi3l1 axis." (PMID 39769202, 2024).
preeclampsia (4 papers, 2020 to 2024). Preeclampsia is a hypertensive disorder of pregnancy that is characterized by new-onset hypertension with proteinuria presenting after 20 weeks of gestation, and depending on mild or severe forms may initially present with severe headache, visual disturbances, and hyperreflexia. "The aim of this study was to investigate the relationship between Chitinase 3-Like 1 gene polymorphisms and the occurrence of preeclampsia in a selected cohort of pregnant women." (PMID 39045955, 2024). "The objective of this study is to investigate any potential correlation between preeclampsia and polymorphisms in the CHI3L1 gene and specifically focus on the influence of polymorphisms in the CHI3L1 gene on the incidence and prognosis of preeclampsia." (PMID 39045955, 2024). "This is a pioneering study, as this is the first to explore the relationship between CHI3L1 gene polymorphisms and preeclampsia." (PMID 39045955, 2024). "The primary finding of our study suggests that the polymorphism rs880633 in the Chitinase-3-like protein 1 (CHI3L1) gene may serve as a protective factor against preeclampsia." (PMID 39045955, 2024). "In summary, our study provides a promising direction for future research, suggesting that the rs880633 polymorphism in the CHI3L1 gene could act as a protective factor against preeclampsia." (PMID 39045955, 2024). "In patients with preeclampsia, elevated levels of Chi3l1 are related to disease severity, which is verified by the difference in Chi3l1 levels in patients with more severe proteinuria and milder proteinuria (median 121.3 ng/mL versus median 55.4 ng/mL; p = 0.022)." (PMID 39769202, 2024).
relapsing-remitting MS (4 papers, 2022 to 2026). "Studies have shown that the levels of CHI3L1 in the cerebrospinal fluid (CSF) are elevated in patients with progressive MS compared to those with relapsing-remitting MS (RRMS)." (PMID 36988727, 2023).
sarcopenia (4 papers, 2022 to 2025). Progressive decline in muscle mass due to aging which results in decreased functional capacity of muscles. "In patients with sarcopenia, CHI3L1 is upregulated and secreted by skeletal muscle via the TNF-α/TNFR1 signaling pathway, protecting myocytes from damage, while concurrently promoting HCC progression by inducing the accumulation of LPO products." (PMID 41568005, 2025). "Among them, the CHI3L1 level was negatively correlated with TC and considerably impairs cholesterol metabolism in individuals with cancer and coexisting sarcopenia." (PMID 39014376, 2024).
streptococcal pneumonia (4 papers, 2014 to 2022). A febrile disease caused by streptococcus pneumoniae. "In a murine model, streptococcal pneumonia induced CHI3L1, and Chi3l1 deletion led to macrophage dysfunction, increased bacterial loads, and reduced survival." (PMID 26366571, 2015). "Conversely, Chi3l1 deletion worsened outcome in a murine model of Streptococcus pneumonia, with increased bacterial burden, lung inflammation, TH1 cytokines, and death." (PMID 25047113, 2014). "It was initially hypothesized that CHI3L1 would decrease pathological TH1 inflammation in ECM, and that, similar to the Streptococcal pneumonia model, Chi3l1 deletion would worsen outcome." (PMID 25047113, 2014).
Anxiety (3 papers, 2016 to 2023). Intense feelings of nervousness, tension, or panic often arise in response to interpersonal stresses. "Thus, it is possible that CHI3L1 deficiency could ameliorate neuroinflammation and reduce anxiety." (PMID 35345530, 2022). "Therefore, in the present study, we investigated whether N-Allyl-2-[(6-butyl-1,3-dimethyl-2,4-dioxo-1,2,3,4-tetrahydropyrido[2,3-d]pyrimidin-5-yl)sulfanyl]acetamide (G721-0282), an inhibitor of CHI3L1, could exert anti-anxiety effects through blockage of CHI3L1-mediated neuroinflammation." (PMID 35345530, 2022). "The results presented in the present study suggest that by interfering with CHI3L1, it alleviated CUMS-induced neuroinflammation and, at the same time, reduced the behavioral characteristics of anxiety." (PMID 35345530, 2022).
chronic heart failure (3 papers, 2015 to 2025). "Several clinical studies show that the plasma level of CHI3L1 increases after MI and remains elevated in chronic heart failure." (PMID 40013912, 2025). "Although we do not know the exact molecular mechanism whereby CHI3L1 governs prolonged inflammation after MI, it appears that inhibition of CHI3L1 may be beneficial to limit cardiac dysfunction in acute and chronic heart failure due to MI." (PMID 40013912, 2025).
depression (3 papers, 2016 to 2023). "In addition, CHI3L1, another member of the carbohydrate binding family, showed significantly increased expression in male LOAD cases with depression vs. LOAD only (log2FC = 1.736, log2FCSE = 0.401, p = 0.030)." (PMID 36421693, 2022).
diffuse astrocytoma (3 papers, 2016 to 2021). A low-grade (WHO grade II) astrocytic neoplasm. "Interestingly, several of these differentially expressed genes identified in our study have also emerged as genes relevant for discriminating distinct subtypes of diffuse astrocytomas in other studies, including the GBM-associated CHI3L1, COL1A1, VEGFA and ANXA genes." (PMID 32647207, 2020).
diffuse large B-cell lymphoma (3 papers, 2021 to 2024). "However, the mechanistic connection between CHI3L1 and immune checkpoint therapy has recently been documented in diffuse large B-cell lymphoma patients." (PMID 33920100, 2021). "Knocking down CHI3L1 can regulate cell cycle inhibition, promote cancer cell apoptosis, and enhance the pro-apoptotic effect of anti-PD-L1 antibodies in vitro and in vivo in diffuse large B-cell lymphoma (DLBCL)." (PMID 38003338, 2023).
emphysema (3 papers, 2013 to 2024). "Macrophages surrounding emphysema and tumor cells were also intensely stained by anti-CHI3L1 antibody (green arrow)." (PMID 23613996, 2013).
esophageal squamous cell carcinoma (3 papers, 2014 to 2021). Esophageal squamous cell carcinoma (ESCC) is a type of esophageal carcinoma (EC) that can affect any part of the esophagus, but is usually located in the upper or middle third. "A previous study also demonstrated that serum CHI3L1 may represent a diagnostic biomarker for esophageal squamous cell carcinoma patients." (PMID 34612767, 2021). "We found the upregulation of CHI3L1 in esophageal squamous cell carcinomas in comparison to normal esophageal tissues." (PMID 34612767, 2021). "Our analysis showed the upregulation of CHI3L1 in esophageal squamous cell carcinomas in comparison to normal esophageal tissues." (PMID 34612767, 2021).
fungal infections (3 papers, 2015 to 2025). "In a model of corneal candidiasis, CHI3L1 is primarily expressed in epithelial cells and exerts protective effects against fungal infection by influencing the expression of anti-inflammatory factors and chemokines through an IL-13Rα-2-dependent mechanism." (PMID 38003338, 2023). "A large amount of data shows that research on CHI3L1 has become increasingly important, as it is involved in disease progression, inflammatory responses, fungal infections, cell activation, and other physiological activities." (PMID 38003338, 2023). "In particular, CHI3L1 has been shown to protect the eye from fungal infections." (PMID 40512033, 2025). "CHI3L1, as a member of the chitinase family, plays an important role in fungal infection models." (PMID 38003338, 2023).
gallbladder cancer (3 papers, 2024 to 2025). "CHI3L1, derived from M2 macrophages, induces gallbladder cancer cells to secrete GDF15 and promotes programmed cell death protein 1 (PD-1) expression via P13K/AKT signaling to inhibit the cytotoxic effect of T cells, leading to the immune escape of tumor cells." (PMID 39068486, 2024).
giant cell arteritis (3 papers, 2010 to 2024). "Giant cell arteritis (GCA) is the most common inflammatory disease of medium and large arteries, and the CD206+MMP-9+ macrophage subset mediates tissue destruction and neovascularization through the Chi3l1/IL-13Rα2 axis in this disease." (PMID 39769202, 2024).
graft versus host disease (3 papers, 2016 to 2022). An immune system disorder that occurs after allogeneic hematopoietic stem cell transplant and is a reaction of donor immune cells against host tissues. "Gene set enrichment analysis showed that Chi3l1 was associated with JAK-STAT signaling, apoptosis, and graft-versus-host disease." (PMID 36277038, 2022). "In addition, knockout of CHI3L1 in donor cells dramatically exacerbated acute graft-versus-host disease by promoting Tfh differentiation and Tfh-related cytokine secretion." (PMID 33664231, 2021).
HIV-associated dementia (3 papers, 2010 to 2025). "CHI3L1 encodes chitinase-3-like protein 1 and is upregulated in macrophages, microglia, and astrocytes associated with MS, AD, and HIV-associated dementia." (PMID 40051633, 2025). "We have previously observed elevated CHI3L1 concentration in the CSF of SIV and HIV encephalitis and therefore wanted to assess its concentration in a broad spectrum of human neurological diseases." (PMID 20540736, 2010). "Recently, we have shown that CHI3L1 expression is induced in the CNS of human and non-human primates with lentiviral encephalitis (HIV encephalitis (HIVE) and SIVE)." (PMID 20540736, 2010).
infarction (3 papers, 2010 to 2025). A localised pathological necrosis of tissue resulting from obstruction of the blood supply usually by a thrombus, an embolus, or vascular torsion. "Kinetic studies of CHI3L1 expression in infarcted hearts further support the conclusion that neutrophils may be the main source of CHI3L1 after infarction." (PMID 40013912, 2025).
Infertility (3 papers, 2021 to 2024). "Seminal Chi3l1 levels are increased in infertile oligoasthenoteratozoospermic (OAT) men with varicocele, and protein levels are negatively correlated with sperm concentration, total sperm motility, and normal sperm morphology." (PMID 39769202, 2024). "Furthermore, serum levels of Chi3l1 are positively correlated with the duration of infertility and the serum level of FSH." (PMID 39769202, 2024). "Our studies demonstrate that CHI3L1 can be neutralized with appropriate antibodies or antagonists or totally knocked out using systemic genetic methodologies without generating tissue and/or organ toxicities or infertility." (PMID 34747367, 2021).
ischemia (3 papers, 2015 to 2023). A hypoperfusion of the BLOOD through an organ or tissue caused by a PATHOLOGIC CONSTRICTION or obstruction of its BLOOD VESSELS, or an absence of BLOOD CIRCULATION. "As ischemia precedes PDR, it may also affect methylation and/or expression of CHI3L1 in subjects with diabetic retinopathy." (PMID 26248552, 2015).
myeloma (3 papers, 2010 to 2018). "Moreover, it was observed that in patients with myeloma elevated serum concentrations of CHI3L1 aggravated bone destruction and were associated with an increase of bone resorption activity hastening the progression of bone disease." (PMID 29547667, 2018).
myositis (3 papers, 2023 to 2025). "Idiopathic inflammatory myopathy (IIM), also known as myositis, is correlated with increased levels of Chi3l1, which potentially predicts myocardial injury in IIM patients." (PMID 39769202, 2024). "Moreover, the infiltration of Chi3l1-positive macrophages into the intramuscular sheath and perimuscular membrane is also detected in the pathogenesis of myositis, and the mechanism by which Chi3l1-positive macrophages contribute to myositis will be a subject of future research." (PMID 39769202, 2024).
non-alcoholic steatohepatitis (3 papers, 2022 to 2025). "Chitinase-3-like 1 protein (CHI3L1) is a secreted glycoprotein, strongly correlated with fibrosis severity in chronic liver diseases including non-alcoholic steatohepatitis (NASH)." (PMID 37166517, 2023).
progressive supranuclear palsy (3 papers, 2017 to 2024). A rare late-onset neurodegenerative disease characterized by supranuclear gaze palsy, postural instability, progressive rigidity, and mild dementia. "In turn, in progressive supranuclear palsy, CHI3L1 was found to be elevated in the CSF and brain tissues and was correlated with disease severity." (PMID 38177294, 2024).
rheumatic diseases (3 papers, 2021 to 2023). "Increased levels of CHI3L1 were reported in several pathologies, including rheumatic diseases and cancer, being involved in inflammation, tissue remodeling and tissue injury in health, as well as during disease." (PMID 34208590, 2021).
Splenomegaly (3 papers, 2014 to 2026). Abnormal increased size of the spleen. "Further, serum CHI3L1 levels were significantly associated with the presence of MF and splenomegaly in patients with lymphoid tumors." (PMID 41937713, 2026).
sporadic amyotrophic lateral sclerosis (3 papers, 2018 to 2023). Sporadic amyotrophic lateral sclerosis is a amyotrophic lateral sclerosis in which there is no known cause, such as no family history. "CHI3L1 expression levels are significantly upregulated in the motor cortex of patients with motor neuron disease in sporadic amyotrophic lateral sclerosis." (PMID 38062768, 2023).
acute coronary syndrome (2 papers, 2022 to 2023). Signs and symptoms related to acute ischemia of the myocardium secondary to coronary artery disease. "Notably, the circulating level of CHI3L1 (i.e., YKL-40) has been investigated as a potential predictive biomarker for prognosis of cancers as well as acute coronary syndrome and MI." (PMID 35625766, 2022).
acute graft versus host disease (2 papers, 2016 to 2025). A syndrome of immunologically mediated tissue damage that may occur following an allogeneic transplant, usually affecting the skin, liver, and GI tract. "In the balance of Th17/Treg cells, the secretion of TGF-β and chitinase-3-like protein 1 (Chi3l1) by UC-MSCs inhibits STAT3 phosphorylation, thereby blocking Th17 cell differentiation and significantly improving acute graft-versus-host disease." (PMID 41488628, 2025).
aneurysm (2 papers, 2014 to 2024). Bulging or ballooning in an area of an artery secondary to arterial wall weakening. "We explore miR-24 regulatory mechanisms, and show that miR-24 regulates inflammation and other critical aneurysm-related processes in a CHI3L1-dependent fashion in M1-subtype macrophages, aortic smooth muscle cells (SMCs) and vascular endothelial cells." (PMID 25358394, 2014). "miR-24 overexpression blocked Chi3l1 induction in vivo, limiting AAA expansion, while anti-miR-24 led to higher Chi3l1 expression and development of larger, rupture-prone aneurysms." (PMID 25358394, 2014). "We explored the regulatory role of miR-24 on inflammation and CHI3L1 expression in HEK293 and aneurysm-related cell types in vitro." (PMID 25358394, 2014). "We also investigated changes in circulating miR-24 plasma expression and Chi3l1 protein levels in our two murine AAA models, and discovered that plasma miR-24 was significantly repressed in mice with aneurysms." (PMID 25358394, 2014).
brain cancer (2 papers, 2010 to 2015). A primary or metastatic malignant neoplasm affecting the brain. "Two similar protein families, namely the fasciclin domain containing protein TGFBI (βig-H3), and chitinase-like proteins, CHI3L1 and CHI3L2, are present in mammals, and recent Massively Parallel Signature Sequencing (MPSS) analysis show similar expression pattern in brain cancer cells." (PMID 21124849, 2010).